RACK1 (receptor for activated C kinase 1)
Description:
Scaffolding protein involved in the recruitment, assembly and/or regulation of a variety of signaling molecules. Interacts with a wide variety of proteins and plays a role in many cellular processes. Component of the 40S ribosomal subunit involved in translational repression. Involved in the initiation of the ribosome quality control (RQC), a pathway that takes place when a ribosome has stalled during translation, by promoting ubiquitination of a subset of 40S ribosomal subunits. Binds to and stabilizes activated protein kinase C (PKC), increasing PKC-mediated phosphorylation. May recruit activated PKC to the ribosome, leading to phosphorylation of EIF6. Inhibits the activity of SRC kinases including SRC, LCK and YES1. Inhibits cell growth by prolonging the G0/G1 phase of the cell cycle. Enhances phosphorylation of BMAL1 by PRKCA and inhibits transcriptional activity of the BMAL1-CLOCK heterodimer. Facilitates ligand-independent nuclear translocation of AR following PKC activation, represses AR transactivation activity and is required for phosphorylation of AR by SRC. Modulates IGF1R-dependent integrin signaling and promotes cell spreading and contact with the extracellular matrix. Involved in PKC-dependent translocation of ADAM12 to the cell membrane. Promotes the ubiquitination and proteasome-mediated degradation of proteins such as CLEC1B and HIF1A. Required for VANGL2 membrane localization, inhibits Wnt signaling, and regulates cellular polarization and oriented cell division during gastrulation. Required for PTK2/FAK1 phosphorylation and dephosphorylation. Regulates internalization of the muscarinic receptor CHRM2. Promotes apoptosis by increasing oligomerization of BAX and disrupting the interaction of BAX with the anti-apoptotic factor BCL2L. Inhibits TRPM6 channel activity. Regulates cell surface expression of some GPCRs such as TBXA2R. Plays a role in regulation of FLT1-mediated cell migration. Involved in the transport of ABCB4 from the Golgi to the apical bile canalicular membrane. Promotes migration of breast carcinoma cells by binding to and activating RHOA. Acts as an adapter for the dephosphorylation and inactivation of AKT1 by promoting recruitment of PP2A phosphatase to AKT1 (By similarity). (Microbial infection) Binds to Y.pseudotuberculosis yopK which leads to inhibition of phagocytosis and survival of bacteria following infection of host cells. (Microbial infection) Enhances phosphorylation of HIV-1 Nef by PKCs. (Microbial infection) In case of poxvirus infection, remodels the ribosomes so that they become optimal for the viral mRNAs (containing poly-A leaders) translation but not for host mRNAs. (Microbial infection) Contributes to the cap-independent internal ribosome entry site (IRES)-mediated translation by some RNA viruses.
Synonyms: HLC-7; GNB2L1; PIG21; Gnb2-rs1; H12.3
Tractability: Small molecule: a structure with a bound ligand is known. Antibody: UniProt places it where antibodies can reach, with high confidence; its Gene Ontology location is reachable by antibodies, with medium confidence. PROTAC: ubiquitination databases record sites on it; its protein half-life has been measured.
Target class: Other cytosolic protein
Gene: Protein-coding gene on chromosome 5 (181,236,897 to 181,248,096, reverse strand). Ensembl gene ENSG00000204628.
Subcellular location: Cell membrane; Cytoplasm; Cytoplasm, perinuclear region; Nucleus; Perikaryon; Cell projection, dendrite; Cell projection, phagocytic cup
Subcellular location (Human Protein Atlas): Nucleoplasm; Cytosol
Pathways (Reactome):
Signal Transduction: Regulation of TNFR1 signaling; TNFR1-induced NF-kappa-B signaling pathway; TNFR1-mediated ceramide production
Cell-Cell communication: Degradation of CDH1
Gene Ontology:
Molecular function: BH3 domain binding; cadherin binding; cyclin binding; enzyme activator activity; enzyme binding; identical protein binding; protein binding; protein homodimerization activity; protein kinase C binding; protein phosphatase binding; protein serine/threonine kinase inhibitor activity; protein tyrosine kinase inhibitor activity; receptor tyrosine kinase binding; ribosome binding; RNA binding; SH2 domain binding; signaling adaptor activity; ion channel inhibitor activity; molecular adaptor activity; signaling receptor binding; translation regulator activity
Biological process: cellular response to glucose stimulus; cellular response to growth factor stimulus; negative regulation of cell growth; negative regulation of gene expression; negative regulation of intrinsic apoptotic signaling pathway in response to hydrogen peroxide; negative regulation of phagocytosis; negative regulation of phosphatidylinositol 3-kinase/protein kinase B signal transduction; negative regulation of protein binding; negative regulation of smoothened signaling pathway; positive regulation of apoptotic process; positive regulation of cell migration; positive regulation of Golgi to plasma membrane protein transport; positive regulation of GTPase activity; positive regulation of proteasomal ubiquitin-dependent protein catabolic process; positive regulation of protein phosphorylation; positive regulation of protein-containing complex assembly; protein ubiquitination; regulation of adenylate cyclase-activating G protein-coupled receptor signaling pathway; regulation of cell cycle; rescue of stalled ribosome; cytoplasmic translation; negative regulation of endoplasmic reticulum unfolded protein response; negative regulation of translation; negative regulation of translational frameshifting; negative regulation of Wnt signaling pathway; and 4 more
Cellular component: cytoplasm; cytosol; extracellular exosome; IRE1-RACK1-PP2A complex; midbody; mitochondrion; nucleoplasm; nucleus; perinuclear region of cytoplasm; phagocytic cup; plasma membrane; cytosolic small ribosomal subunit; dendrite; neuronal cell body; perikaryon; small ribosomal subunit; cell body; neuron projection
Genetic constraint (gnomAD): Loss-of-function variants: 3 observed, 32.35 expected, observed/expected ratio (o/e) 0.0927, 90% interval 0.041 to 0.24. The upper end of that interval is the gene's LOEUF score, 0.24, which puts it in group 1 of 6, group 1 being the genes least tolerant of losing a copy. Missense variants: 127 observed, 356.86 expected, observed/expected ratio (o/e) 0.36, 90% interval 0.31 to 0.41. Synonymous variants: 156 observed, 140.13 expected, observed/expected ratio (o/e) 1.11, 90% interval 0.98 to 1.27.
Homologues: Orthologues: dog RACK1 (100% identical), guinea pig RACK1 (100% identical), macaque RACK1 (100% identical), mouse Rack1 (100% identical), pig RACK1 (100% identical), rat Rack1 (100% identical), rabbit RACK1 (98% identical), zebrafish rack1 (96% identical), tropical clawed frog rack1 (95% identical), chimpanzee RACK1 (84% identical), Drosophila melanogaster Rack1 (77% identical), Caenorhabditis elegans rack-1 (73% identical).
Diseases named in the same sentence as RACK1 in open-access papers:
RACK1 is named in the same sentence as 153 diseases in open-access papers, as found by Europe PMC text mining. Sharing a sentence is not in itself a finding about the gene and the disease. The quoted sentences say what the papers report.
breast cancer (45 papers, 2008 to 2025). A primary or metastatic malignant neoplasm involving the breast. "RACK1 overexpression is linked to more aggressive forms of cancers, including prostate, colorectal, and breast cancers, as well as hepatocellular carcinoma, nasopharyngeal carcinoma, and non-small cell lung cancer." (PMID 39458945, 2024). "We further identified that CCDC102B was stabilized by the loss of RACK1, a protein negatively correlated with breast cancer metastasis." (PMID 35957886, 2022). "Our findings suggest that the interaction between Anxa2 and Rack1/Src is responsible for the association between drug resistance and aggressive behavior in breast cancer cells." (PMID 31113450, 2019). "In this work, we further explored the effect of Rack1 on the invasive and metastatic potential in drug-resistant breast cancer cells, and investigated the mechanism underlying the regulation of Anxa2 Tyr23 phosphorylation." (PMID 31113450, 2019). "The interaction between Anxa2 and Rack1/Src is responsible for the association between drug resistance and invasive/metastatic potential in breast cancer cells." (PMID 31113450, 2019). "Recently, RACK1 upregulation was found to be part of the gene signature associated with shorter metastasis-free survival in breast cancer patients." (PMID 18442364, 2008). "Herein, RACK1 silencing inhibited breast cancer proliferation in vitro and tumor growth in vivo, whereas restoration of RACK1 expression in RACK1-deficient cells rescued the proliferative activity, supporting that RACK1 is required for breast cancer cell proliferation." (PMID 37848434, 2023). "LncRNA prostate cancer-associated transcript-1 (PCAT-1) is induced upon hypoxia in breast cancer cells and stabilizes HIF1α by directly interacting with the receptor of activated protein C kinase-1 (RACK1) protein and preventing RACK1-mediated degradation of HIF1α." (PMID 37583933, 2023). "Overexpression of RACK1 has been strongly linked to advanced clinical stage and poor prognosis in a variety of solid cancers, and it was especially accurate as a prognostic indicator in breast cancer, but its prognostic value in glioma remained unclear." (PMID 27763568, 2016). "Our in vitro and in vivo evidence suggests that RACK1 is required for breast cancer cell proliferation by regulating cell cycle progression." (PMID 37848434, 2023). "In conclusion, our results suggest that RACK1 facilitates breast cancer progression by enhancing the stability of β-catenin." (PMID 37848434, 2023). "Our previous studies have shown that RACK1 is essential for the drug resistance and metastasis of breast cancer cells." (PMID 37848434, 2023). "Collectively, we identified PSMD2 as a novel binding partner of RACK1 and β-catenin in breast cancer cells." (PMID 37848434, 2023). "Collectively, our findings suggest that RACK1 promotes breast cancer cell proliferation by regulating cell cycle progression." (PMID 37848434, 2023). "Here, we show that RACK1 is required for the proliferation of breast cancer cells by enhancing the stability of β-catenin and activating the canonical WNT pathway." (PMID 37848434, 2023). "Collectively, our findings suggest that RACK1 facilitates breast cancer progression by competitively inhibiting β-catenin binding to PSMD2, increasing β-catenin stability, and promoting WNT pathway activation." (PMID 37848434, 2023). "Taken together, these results suggest that RACK1 promotes breast cancer proliferation by regulating β-catenin stability and WNT pathway activation." (PMID 37848434, 2023). "The knockdown of RACK1 significantly decreased the protein level of β-catenin in five breast cancer cell lines." (PMID 37848434, 2023). "Collectively, our findings uncover a novel mechanism by which RACK1 increases β-catenin stability and promotes breast cancer proliferation." (PMID 37848434, 2023). "The mechanisms by which RACK1 regulates β-catenin stability in breast cancer cells are worthy of investigation." (PMID 37848434, 2023).
breast cancer (continued). "Taken together, these results suggest that RACK1 promotes breast cancer cell proliferation by affecting β-catenin protein levels and promoting cell cycle progression." (PMID 37848434, 2023). "We and others had identified RACK1 as a key driver of the malignant biology of multiple tumors, including breast cancer, non-small cell lung cancer and OC." (PMID 37828084, 2023). "Collectively, RACK1 competes with β-catenin for binding to the Armadillo-like helical domain of PSMD2 in breast cancer cells." (PMID 37848434, 2023). "RACK1 was silenced in five breast cancer cell lines by two different lentivirally expressed shRNAs, one of which targeted the non-coding region of RACK1 for future rescue assays." (PMID 37848434, 2023). "In this study, we sought to investigate the function and potential mechanisms of RACK1 in breast cancer cell proliferation." (PMID 37848434, 2023). "For instance, previous studies, including ours, have shown that RACK1 is required for breast cancer cell invasion and metastasis; however, a recent study reported that RACK1 has a negative regulatory effect on breast cancer metastasis." (PMID 37848434, 2023). "Here, we found that RACK1 silencing significantly increased the ubiquitination level of β-catenin and accelerated its degradation in breast cancer cells and vice versa, suggesting that RACK1 regulate the stability of β-catenin protein through the UPS." (PMID 37848434, 2023). "Collectively, RACK1 is required for breast cancer cell proliferation in vitro and tumor growth in vivo." (PMID 37848434, 2023). "We have previously shown that RACK1 enhances the invasive and metastatic potential of breast cancer cells and modulates their drug sensitivity." (PMID 37848434, 2023). "Here, we show that RACK1 is required for breast cancer cell proliferation in vitro and tumor growth in vivo." (PMID 37848434, 2023). "We also examined the expression of RACK1 in The Cancer Proteome Atlas (TCPA) database and found that RACK1 protein expression was higher in breast cancer tissues than in normal tissues." (PMID 37848434, 2023). "In contrast, RACK1 is upregulated and promotes tumor progression in hepatocellular carcinoma, breast cancer and lung adenocarcinoma." (PMID 37828084, 2023). "Knockdown of RACK1 significantly reduced proliferation in all breast cancer cell lines as measured by CCK-8 and colony formation assays." (PMID 37848434, 2023). "For non-digestive cancers, including non-small cell lung cancer (NSCLC), breast cancer (BC), and glioma, RACK1 is a significant biomarker of poor prognosis." (PMID 37601269, 2023). "Collectively, our findings uncover a novel mechanism by which RACK1 enhances β-catenin stability and promotes breast cancer proliferation." (PMID 37848434, 2023). "To validate the role of RACK1 in breast cancer, we analyzed the expression with qRT–PCR in breast cancer patients with LN metastasis (n=20) and found that RACK1 was similarly expressed in LN metastatic loci and primary tumors (P=0.7543)." (PMID 35957886, 2022). "On the other hand, the enhancement of the migration of RACK1 knockout breast cancer cells was attenuated by CCDC102B knockout." (PMID 35957886, 2022). "In fact, both in vitro and in vivo studies have shown that RACK1 promotes the proliferation, invasion, and metastasis of breast cancer, and it remains one of the independent predictors of poor clinical outcomes in breast cancer." (PMID 36009568, 2022). "Taken together, our results demonstrated that RACK1 inhibits breast cancer metastasis by decreasing the stability of CCDC102B." (PMID 35957886, 2022). "To further verify this, we performed functional rescue tests in breast cancer cells, showing that RACK1-reduced cell migration was remarkably enhanced in NF−κB activated cells." (PMID 35957886, 2022). "The bc-GenExMiner 3.0 database was used to explore the correlation between RACK1 expression and nodal status in breast cancer patients." (PMID 35957886, 2022).
breast cancer (continued). "Numerous studies have shown that Rack1 was anomalously expressed in multiple types of human cancers including breast cancer, lung cancer, colorectal cancer, and liver cancers." (PMID 34480519, 2021). "Recent data indicate that receptor for activated C kinase 1 (RACK1) is a putative prognostic marker and drug target in breast cancer (BC)." (PMID 33311444, 2020). "The interaction between Anxa2 and Rack1/Src is responsible for the association between MDR and invasive potential in breast cancer cells." (PMID 31113450, 2019). "Collectively, these data demonstrated that Rack1 is critical for the metastatic potential of drug-resistant breast cancer cells in vivo." (PMID 31113450, 2019). "Rack1 knockdown decreases Adriamycin-triggered Tyr23 phosphorylation of Anxa2 in drug-resistant breast cancer." (PMID 31113450, 2019). "Rack1 is required for the invasive and metastatic potential of drug-resistant breast cancer cells through modulating Anxa2 phosphorylation." (PMID 31113450, 2019). "We previously reported that Rack1 is required for the migration and invasion potential of drug-resistant breast cancer cells." (PMID 31113450, 2019). "Changes in RACK1 expression have been recorded in various cancers including colon, gastric, lung and breast cancer." (PMID 30112187, 2018). "Recently, researchers have found the high expression of RACK1 in a multitude of tumors such as melanomas, breast cancer, colorectal cancer, pulmonary adenocarcinoma, hepatoma, esophageal squamous cell carcinoma, and oral squamous cell carcinomas." (PMID 27170279, 2016). "In breast cancer cells, PP2A associates with the scaffolding protein RACK1 in an IGF-1 dependant manner and regulates cell migration and proliferation by controlling the formation of a complex between the IGF-IR, RACK1 and β1 integrin." (PMID 25867001, 2015). "Similarily, the Receptor for activated C kinase 1 (RACK1) has been shown to confer paclitaxel resistance to breast cancer cells by binding to both the dynein light chain 1 and BimEL upon exposure to paclitaxel." (PMID 26405162, 2015). "RACK1’s relevance to cancer progression was first demonstrated in breast cancer where its expression serves as an independent prognostic factor for poor outcome." (PMID 23866081, 2013). "Specifically, RACK1 expression is being assessed as a prognostic indicator in breast cancer, where increased RACK1 expression is strongly related to advanced clinical stage." (PMID 21978545, 2011). "Notably, RACK1 is upregulated in cancers like colorectal adenocarcinoma, hepatocellular carcinoma, breast cancer, non-small cell lung cancer, and melanoma, highlighting its significant role in cancer progression and development." (PMID 39458945, 2024). "To determine how RACK1 regulates the proliferative capacity of breast cancer cells, we performed a co-immunoprecipitation (IP) assay using anti-Flag antibodies in previously obtained RACK1-flag-expressing MDA-231 cells and analyzed the IP product by mass spectrometry." (PMID 37848434, 2023). "Interestingly, several studies have shown that ribosomal RACK1 plays a role in promoting the progression of breast cancer, neuroblastoma and hepatocellular carcinoma." (PMID 37848434, 2023). "The present study supports the tumor-promoting role of RACK1 in breast cancer." (PMID 37848434, 2023). "To test whether this mechanism is also present in breast cancer cells, we performed a Co-IP assay in breast cancer cells using anti-RACK1 and anti-β-catenin antibodies." (PMID 37848434, 2023). "As a scaffolding protein, the binding partners of RACK1 in gastric cancer cells may be very different from those in breast cancer cells, resulting in a potentially different or even opposite role for RACK1 in downstream signaling regulation." (PMID 37848434, 2023). "Moreover, inhibition of the proteasome by MG-132 also increased poly-ubiquitinated β-catenin levels in two RACK1-silenced breast cancer cells." (PMID 37848434, 2023).